DPYSL4 (dihydropyrimidinase like 4)
Description:
Necessary for signaling by class 3 semaphorins and subsequent remodeling of the cytoskeleton. Plays a role in axon guidance, neuronal growth cone collapse and cell migration (By similarity).
Synonyms: DRP-4; CRMP3; ULIP4
Tractability: PROTAC: ubiquitination databases record sites on it; its protein half-life has been measured.
Gene: Protein-coding gene on chromosome 10 (132,186,897 to 132,205,762, forward strand). Ensembl gene ENSG00000151640.
Subcellular location: Cytoplasm
Subcellular location (Human Protein Atlas): Mitochondria; Vesicles
Pathways (Reactome):
Developmental Biology: CRMPs in Sema3A signaling
Gene Ontology:
Molecular function: filamin binding; protein binding; dihydropyrimidinase activity; hydrolase activity; hydrolase activity, acting on carbon-nitrogen (but not peptide) bonds
Biological process: nervous system development; pyrimidine nucleobase catabolic process
Cellular component: cytosol; cytoplasm
Genetic constraint (gnomAD): Loss-of-function variants: 44 observed, 63.85 expected, observed/expected ratio (o/e) 0.69, 90% interval 0.54 to 0.89. The upper end of that interval is the gene's LOEUF score, 0.89, which puts it in group 3 of 6, group 1 being the genes least tolerant of losing a copy. Missense variants: 733 observed, 830.35 expected, observed/expected ratio (o/e) 0.88, 90% interval 0.83 to 0.94. Synonymous variants: 353 observed, 336.6 expected, observed/expected ratio (o/e) 1.05, 90% interval 0.96 to 1.14.
Homologues: Orthologues: chimpanzee DPYSL4 (99% identical), rat Dpysl4 (94% identical), guinea pig DPYSL4 (93% identical), mouse Dpysl4 (93% identical), dog DPYSL4 (93% identical), macaque DPYSL4 (89% identical), pig DPYSL4 (88% identical), rabbit DPYSL4 (87% identical). Paralogues in human: DPYSL2 (74% identical), DPYSL3 (69% identical), CRMP1 (68% identical), DPYS (51% identical), DPYSL5 (48% identical).
Diseases named in the same sentence as DPYSL4 in open-access papers:
DPYSL4 is named in the same sentence as 20 diseases in open-access papers, as found by Europe PMC text mining. Sharing a sentence is not in itself a finding about the gene and the disease. The quoted sentences say what the papers report.
hepatocellular carcinoma (2 papers, 2019 to 2020). A malignant tumor that arises from hepatocytes. "(2019) suggested that DPYSL4 is significantly associated with OS in hepatocellular carcinoma." (PMID 33344083, 2020). "We identified six mRNAs (DPYSL4, HOMER1, ABCB6, CENPA, CDK1, STMN1) significantly associated with overall survival in the Cox proportional regression model for hepatocellular carcinoma." (PMID 31790363, 2019).
medulloblastoma (2 papers, 2014 to 2023). A malignant, invasive embryonal neoplasm arising from the cerebellum. "Semaphorin (co-expression network, p<1.23×10−5) and dopamine (intersect analysis, p<0.02) signaling pathways were exclusively enriched in Group 4 medulloblastoma and connected via co-expressed genes, DPYSL4, RND2 and SNCAIP that are all part of the same network cluster." (PMID 25412507, 2014). "Additional novel findings from our analysis indicate that Group 4 medulloblastoma over-express semaphorin signalling molecules, including DPYSL3 and DPYSL4, which regulate neuronal differentiation and apoptosis in the context of synaptic pruning." (PMID 25412507, 2014).
ovarian carcinoma (2 papers, 2023 to 2025). A malignant neoplasm originating from the surface ovarian epithelium. "For ovarian cancer, Kaplan–Meier survival analyses have shown that DPYSL4 is associated with poor survival in ovarian cancer." (PMID 37605299, 2023). "Low DPYSL4 expression is associated with poor survival in breast and ovarian cancers." (PMID 40739397, 2025).
geographic atrophy (1 paper, 2022). "The identification of eQTL in genes encoding mitochondrial proteins and respiratory complexes, such as MTG2 and DPYSL4 further suggests that variations in mitochondrial activities in the RPE might be at play in the progression of geographic atrophy." (PMID 35882847, 2022). "DPYSL4 in RPE1 (rs56307927) and RPE3 (rs2818409) were other eQTL where genotype had a significant interaction with disease, resulting in increased expression of this transcript in geographic atrophy cell lines." (PMID 35882847, 2022).
glioma (1 paper, 2025). A benign or malignant brain and spinal cord tumor that arises from glial cells (astrocytes, oligodendrocytes, ependymal cells). "DPYSL4 is highly expressed in glioma cells to regulate neuronal differentiation and apoptosis." (PMID 40739397, 2025).
Intellectual disability (1 paper, 2015). "Furthermore, it has been suggested that DPYSL4 gene deletion could be associated with behavioral problems and/or intellectual disability because its function is involved in neuronal differentiation." (PMID 26294985, 2015).
mastitis (1 paper, 2024). Inflammation of breast tissue during lactation or postpartum due to an obstructed duct or infection. "The same region partially overlaps the CNVR_1549_P (the region comprising the JAKMIP3, DPYSL4, STK32C, LRRC27, PWWP2B) resulted associated with clinical mastitis in Mexican Holstein Cattle." (PMID 38771855, 2024).
Obesity (1 paper, 2020). Accumulation of substantial excess body fat. "The authors thus suggested that CRMP3/DPYSL4 is linked to the pathophysiology of both cancer and obesity, supporting our hypothesis regarding the involvement of CRMP in metabolic homeostasis." (PMID 32245267, 2020).
ovarian tumor (1 paper, 2022). "Dihydropyrimidinase-like 4 (DPYSL4), a member of the collapsin response mediator protein family, is involved in ovarian tumor development." (PMID 36147929, 2022).
cancer (7 papers, 2013 to 2025). A tumor composed of atypical neoplastic, often pleomorphic cells that invade other tissues. "DPYSL4 is associated with mitochondrial supercomplexes, stimulates ATP production, and suppresses cancer cell invasion." (PMID 36694200, 2023). "DPYSL4 is a member of the collapsin response mediator protein family, which is involved in cancer invasion and progression." (PMID 40302814, 2025). "We further analyzed the differential expression of DPYSL4, HOMER1, ABCB6, CENPA, CDK1, STMN1 in cancer and adjacent tissues, and found that compared with adjacent tissues, the six genes in 309 HCC tissues were significantly up-regulated (P<0.01)." (PMID 31790363, 2019).
tumor (5 papers, 2019 to 2025). "DPYSL4, a member of the collapse response regulatory protein family, is considered to be involved in tumor progression." (PMID 37670265, 2023). "Mouse xenograft and lung metastasis models have shown that DPYSL4 expression inhibits tumor growth and metastasis in vivo." (PMID 37670265, 2023). "DPYSL4 was exclusively upregulated in the siPFKBF4 100 nM/DOX group as an apoptotic agent compared to downregulation in other monotherapy groups, indicating synergistic effects of siRNA and chemotherapy against tumor growth and invasion." (PMID 40739397, 2025).
DPYSL4 also shares sentences with these, for which no sentence is quoted: encephalitis (2 papers); schizophrenia (2); cognitive deficits (1); cyst (1); depression (1); encephalomyelitis (1); Myelopathy (1); paraneoplastic neurologic syndrome (1); small cell lung carcinoma (1).